LATS1 (large tumor suppressor kinase 1)
Diseases named in the same sentence as LATS1 in open-access papers (continued):
Sharing a sentence is not in itself a finding about the gene and the disease.
tumor (continued). "Our follow up studies, using mass-spectrometry based proteomics, identified the human tumour suppressors LATS1 and RASSF1A as MST2 interactors that mediated the pro-apoptotic signal downstream of RAF1 upon apoptotic stimuli." (PMID 27322327, 2016). "Ectopic expression of LATS1 decreased GC cell proliferation and invasion in vitro and inhibited tumor growth and liver metastasis in vivo, but depletion of LATS1 expression restored the invasive phenotype." (PMID 26921249, 2016). "Then, the tumour samples were removed for immunohistochemical analysis of E-cadherin, LATS1 and YAP expression." (PMID 25712415, 2015). "The pattern of equal distribution of LATS1/2 nonsense or frame-shift mutations is consistent with the idea that LATS1 and LATS2 are tumor suppressor genes." (PMID 25482410, 2015). "Intriguingly, recent studies have shown that most of the Hippo core tumor suppressor proteins, such as Mst1/2, Lats1/2, WW45, Mob1 are involved in regulating mitosis." (PMID 26375055, 2015). "LATS1 as a tumour suppressor plays an important role in the control of tumour development and tumourigenesis by negatively regulating cell proliferation and modulating cell survival." (PMID 25712415, 2015). "The development of tumours in LATS1 null mice has been reported more than 15 years ago, but this specific research aspect has not been pursued further since then." (PMID 25097725, 2014). "In mammals, genetic studies provided the same picture, namely that loss of MST1/2, MOB1A/B, or LATS1 results in tumour growth, while YAP overexpression is sufficient to induce tumours." (PMID 23985307, 2013). "Taken together, LATS1/2 play important roles in embryonic development and heart formation, besides functioning as tumour suppressors in mammals." (PMID 23985307, 2013). "In conclusion, our study has identified WWP1 E3 ligase as a novel negative regulator of LATS1 tumor suppressor stability." (PMID 23573293, 2013). "By screening members of the NEDD4-like family ubiquitin ligases that play important roles in cancer, we have identified WWP1 as a novel negative regulator of LATS1 tumor suppressor stability." (PMID 23573293, 2013). "From our studies, WWP1 and Itch serve to balance LATS1 tumor suppressor activity through continuous ubiquitination and degradation of LATS1 under physiological (unstressed) condition." (PMID 23573293, 2013). "LATS1 (large tumor suppressor 1) is a serine/threonine (ser/thr) kinase of the AGC kinase family and a novel tumor suppressor gene that is mutated or down-regulated in a variety of human cancers." (PMID 23573293, 2013). "Overexpression of human LATS1 in MEF cells and human tumor cell lines caused the inhibition of Cdc2 kinase activity and this was associated with cell cycle arrest in G2/M or apoptosis." (PMID 19656388, 2009). "There is solid genetic evidence in Drosophila and mice to establish the role of LATS1 as a tumor suppressor." (PMID 19656388, 2009). "Although this finding is consistent with the fact that CUX1 activates Lats1 transcription, there is an apparent discrepancy between the elevated expression of Lats1 in tumors from transgenic mice and the purported role of LATS1 as a tumor suppressor." (PMID 19656388, 2009). "Complementation assays in flies demonstrated that the human LATS1 gene was able to suppress tumour growth and rescue all developmental defects of wts mutants including embryonic lethality." (PMID 19656388, 2009). "Through this inhibition, LATS1/2 performs a crucial tumor-suppressive function." (PMID 39757214, 2025).
tumor (continued). "LATS1 is a tumor suppressor in the Hippo core kinase cascade." (PMID 41338457, 2025). "Furthermore, Src phosphorylates and inhibits LATS1, a key kinase in the Hippo pathway, thereby reducing its tumor suppressor function." (PMID 40895190, 2025). "Notably, most of these genes (Kmt2d, Bcor, Smad, Nf2, Lats1) are tumor suppressors in human cancers." (PMID 38853928, 2025). "Therefore, the upregulation of these signals in Lats1/2-null tumor cells suggest that they contribute to the recruitment and activation of the CAF populations observed in the stroma of these mice." (PMID 39953252, 2025). "Another regulator of the Hippo signaling pathway is LATS1/2 which has a tumor suppressive property." (PMID 40106220, 2025). "Moreover, RASSF6 directly activates the Hippo pathway by enhancing the phosphorylation of STK4/3 and LATS1/2 kinases, thereby reinforcing its role as a critical upstream activator of Hippo tumor-suppressive signaling." (PMID 41153630, 2025). "It is clear that SAV1 and LATS1/2 play essential roles in tumor suppression." (PMID 38920690, 2024). "YAP/TAZ are commonly identified as oncogenes and MST1/2 and LATS1/2 as tumor suppressors, although recent evidence suggests that LATS1/2 kinases may also act as oncogenes." (PMID 39697631, 2024). "Their findings attempt to establish novel cooperation and coordination between oncogenic Rho GTPase/F-actin function and the tumor-suppressive LATS1/2 (Hippo pathway) as two synergistic components of the STARD13-correlated ceRNA in modulating breast CSC characteristics." (PMID 39170516, 2024). "In some tumor cells, MST1/2 and LATS1/2 may prevent phosphorylation of YAP1, causing its translocation to the nucleus, where it functions as a transcription factor that promotes proliferation, invasion, and metastasis." (PMID 39313797, 2024). "Surprisingly, LATS1 phosphorylation of YAP1 may also indirectly promote the growth of a small population of cancer cells named tumor-repopulating cells (TRCs)." (PMID 38920690, 2024). "Collectively, these results indicate that LATS1/2 loss impairs the infiltration of CD8+ T cells in tumors and may hinder anti-tumor immunity by suppressing MHC-I expression." (PMID 38383447, 2024). "Lats1 immunoreactivity, more evident in the cytoplasm, negatively correlated with ccRCC tumor size." (PMID 39123485, 2024). "Consistent with this hypothesis, tumor proliferation, survival, and invasion were inhibited by YTHDF2 depletion, and this tumor suppressive effect was rescued by inhibiting the expression of LATS1." (PMID 36609396, 2023). "However, acetylation of LATS1 blocked Hippo signaling, converting LATS1 from a tumor suppressor to a tumor promoter." (PMID 37799806, 2023). "Decreased expression of LATS1 or LATS2 leads to tumor enlargement and lymph node metastasis." (PMID 37548821, 2023). "Interestingly and paradoxically, emerging evidence suggests that YAP has tumor-suppressing functions and that LATS1/2 have tumor-promoting functions via interactions with other signaling pathways or modulating cancer microenvironment." (PMID 37735707, 2023). "Indeed, Nkx2-2as functions as a ceRNA, sequestering miR-103/107 and miR-548 that target BTG2/Tis21/PC3 and LATS1/2 tumor suppressors, consequently its downregulation fosters tumor growth both in vitro and in vivo." (PMID 38004481, 2023). "Indeed, neutrophils in the tumor tissue showed the highest protein levels of YAP/TAZ but reduced expression levels of LATS1/2 compared to those from other tissues." (PMID 36921037, 2023). "Merlin, also known as the protein neurofibromin 2 (NF2), is a widely studied tumor suppressor that activates the Hippo pathway to inhibit YAP/TAZ activity via the mechanism of targeting LATS1/2 and improving the phosphorylation and activation of YAP/TAZ by MST1/2." (PMID 37243813, 2023).
tumor (continued). "Therefore, we consider that the administration of therapeutic apigenin reduces LATS1 gene expression in cancer cells and plays a suppressive role in tumor formation." (PMID 36721804, 2023). "Deep deletions were predominantly observed in LATS1/2, underscoring its tumor-suppressing role." (PMID 38067201, 2023). "LATS1/2 kinases are reported to be tumour suppressors in many cancers." (PMID 36443313, 2022). "Furthermore, LATS1/2 ablation improves tumor immunogenicity and suppresses tumor growth both in vivo and in vitro." (PMID 35743763, 2022). "Together, our data suggest that LATS1 may impose a barrier to bolster luminal cell identity and restrict cancer cell plasticity also in vivo, which may restrain tumor growth and curb its metastatic potential." (PMID 36443319, 2022). "Interestingly, the pattern of distribution of H3K36me2, which was enriched in the luminal tumor subpopulation and augmented in WT relative to Lats1-depleted cells, was opposite to that of H3K27ac." (PMID 36443319, 2022). "Furthermore, our data suggest that the LATS1 tumor suppressor restrains luminal-to-basal-like plasticity through LATS1–NCOR1–HDAC1-mediated H3K27 deacetylation of ERα-repressed regions." (PMID 36443319, 2022). "While it is well-described that Lats1/2 loss functionally inactivates the Hippo pathway and leads to the activation of YAP and TAZ, LATS1/2 can also impinge upon additional signaling pathways that promote tumor development." (PMID 35768444, 2022). "Combined deletion of MINK1 and MST1/2 could inhibit the activation of LATS1/2, improve tumor immunogenicity, and inhibit tumor growth." (PMID 36303542, 2022). "LATS1 is found to decrease GC cell proliferation and invasion in vitro, and tumour growth and metastasis in vivo, by inhibiting YAP nuclear translocation and, thus, expression of pro-proliferative and pro-invasive target genes, among which are YAP, CTGF, PCNA, MMP-2, and MMP-9." (PMID 35565411, 2022). "Alternatively, given recent studies showing that Hippo pathway in tumor may be affected by intracellular calcium levels, it is also possible that phosphorylation of LATS1 may be inhibited by intracellular calcium, which activates certain phosphatases." (PMID 35942515, 2022). "Since its discovery in Drosophila, LATS1/2 has been considered a tumor suppressor." (PMID 35409214, 2022). "Further molecular analyses will reveal whether any of the known tumor suppressors in this region, e.g., LATS1, PARK2, or PLAGL1, is the target of these deletions in ACC." (PMID 35954356, 2022). "The Hippo pathway's primary kinase component, LATS1, has been hypothesized as a tumor suppressor in a variety of cancers 14-20." (PMID 35003351, 2021). "Furthermore, RT-qPCR results showed that the LATS1 mRNA level was lower in the HCC tissues (n = 30) than in the paired non-tumor tissues (n = 30)." (PMID 34565286, 2021). "The LATS1 kinase has been described as a tumor suppressor in various cancers." (PMID 33803640, 2021). "We first investigated the methylation of all the promoters of the genes involved in the RASSF/Hippo pathway, specifically RASSF1/2, STRK4/3 (coding for MST1 and MST2 proteins respectively), and LATS1/2, by MS-PCR using DNA extracted from the tumour blocks of 100 patients." (PMID 34885067, 2021). "Furthermore, the expression of PDS5B and LATS1 was determined in mouse tumor tissues by western blotting." (PMID 34226509, 2021). "However, ITCH has been found to play contrasting roles in mediating Hippo signalling and cancer promotion by degrading LATS1, a known tumour suppressor." (PMID 34831354, 2021). "Specifically, our in vivo experiments showing a significant but more limited response to erlotinib in LATS1/2 KO group and rapid tumor regrowth after erlotinib treatment support the idea that YAP/TAZ activation plays an important role in therapy resistance and in tumor recurrence." (PMID 34725466, 2021).
tumor (continued). "Interestingly, p‐Src levels are also reduced upon treatment with Porc inhibitor, possibly reflecting a role of the Wnt target gene CD44 in promoting Src activation and LATS1/2 inhibition in crypts, similar to its function in other cell and tumour types." (PMID 33950519, 2021). "Loss-of-function of the tumor suppressors (MST1/2, LATS1/2, SAV1 etc.)and activation of transcriptional coactivators YAP/TAZ (caused by protein overexpression and/or enhanced nuclear accumulation) play important roles in tumorigenesis and cancer-associated malignant features." (PMID 33467099, 2021). "We next investigated the pathological features of the LATS1/2 cKO tumours." (PMID 32404936, 2020). "LATS2 like LATS1 is a tumor suppressor in the Hippo signaling pathway." (PMID 33247672, 2020). "HOPX protein was increased in nlsYAP5SA mice and in LATS1/2 cKO tumours." (PMID 32404936, 2020). "Finally, the effect of MGO on LATS1 is in keeping with the previous finding that MGO favours proteasome degradation of this tumour suppressor." (PMID 32778157, 2020). "Tumor cells with LATS1/2 deficiency secreted nucleic acid-rich EVs to facilitate TLRs-Myd88/TRIF signaling and type I IFN production, which accelerated DC maturation, CD8+ T lymphocyte expansion, and tumor growth arrest." (PMID 32849504, 2020). "Interestingly, cytokeratin 18, a marker expressed in the ependymal layer and in our LATS1/2 cKO tumours was among the top 10 increased genes in nlsYAP5SA mice." (PMID 32404936, 2020). "Tumor growth of U251-sh-PMEPA1a cells increased with knockdown of LATS1 or overexpression of YAP." (PMID 31605013, 2020). "HOPX co-localised with cells expressing nuclear YAP1 in LATS1/2 cKO tumours." (PMID 32404936, 2020). "Mechanistic investigations revealed that NR1B2 might be a tumor suppressor to inhibit EMT through the LATS1/2-YAP pathway." (PMID 31391070, 2019). "More importantly, NR1B2 might be a tumor suppressor through LATS1/2-YAP pathway, which not only sheds new light on KIRC progression and metastasis, but also provides a potential target for cancer prevention and treatment." (PMID 31391070, 2019). "In conclusion, our results indicate that miR-29c-3p acts as a tumor suppressor in HCC by targeting DNMT3B and the LATS1-associated Hippo signaling pathway, which might represent a novel potential therapeutic target for HCC." (PMID 30718452, 2019). "Indeed, RNAi-mediated ablation of LATS1 expression results in an increase of Srf-induced apoptosis and a reduction of cell viability in vitro and a decrease of tumor growth in vivo." (PMID 31848340, 2019). "One identified candidate was the tumor suppressor LATS1 known to suppress breast tumorigenesis." (PMID 30710319, 2019). "Additionally, overexpression of Lats1 reversed the knocking down CRABP2 expression results promoting tumor cells invasion and metastasis by monolayer wound healing and transwell assays." (PMID 31419991, 2019). "Finally, the correlation between LATS1 mRNA expression and Srf response was explored in a local patient cohort where serial and paired tumor and non-tumor biopsies were taken and analyzed before and during Srf therapy." (PMID 31848340, 2019). "Next, DNMT3B expression was positively correlated with tumor size, vascular invasion, and intrahepatic metastasis (p < 0.005), and LATS1 expression was positively correlated with tumor size, TNM (tumor, node, metastasis) stage, and intrahepatic metastasis (p < 0.005)." (PMID 30718452, 2019). "Typically in quiescent cells, Yap1 is phosphorylated downstream of the tumor suppressive Hippo pathway, by Lats1 and Lats2 kinases; phosphorylation leads to its sequestration in the cytoplasm by 14–3-3 proteins resulting in proteasomal degradation, thereby preventing its nuclear import." (PMID 30322398, 2018). "LATS1 immunoreactivity in cancer cells negatively correlated with the size of primary tumor." (PMID 29850494, 2018).
tumor (continued). "Recent studies show that LATS1 is a central regulator of an emerging tumor suppressor pathway termed the Hippo-LATS/Warts pathway that suppresses tumor growth, and we also found that LATS1 could suppress GC cells proliferation." (PMID 29374493, 2018). "Based on these observations, the authors suggest that controlled targeting of LATS1/2 may prove therapeutically efficacious in enhancing tumour immunogenicity in B16-OVA melanoma, 4T1 breast cancer, and SCC7 squamous cell carcinoma mouse models." (PMID 29597279, 2018). "LATS1 immunoexpression was found only in the cytoplasm of tumor cells and PCT epithelium." (PMID 29850494, 2018). "Either way, we propose that compromised LATS1 expression may be conducive to enhanced tumor cell plasticity, facilitating escape from hormone therapy." (PMID 30456386, 2018). "The hippo signaling pathway plays profound roles in both cell density control and anti-tumor because LATS1/2 phosphorylates the transcriptional coactivators, promoting its cytoplasmic localization, preventing the expression of anti-apoptotic genes and inducing apoptosis and restricting cell density." (PMID 29892231, 2018). "Another recent study has also shown that the loss of the Hippo pathway kinases large tumour suppressor 1 and 2 (LATS1/2) in tumour cells inhibits tumour growth by nucleic-acid-rich-EVs, which induce a type I interferon response (IFN) via the Toll-like receptors-MYD88/TRIF pathway." (PMID 29158316, 2018). "LATS1 immunoexpression in cancer cells negatively correlated with the size of primary tumor." (PMID 29850494, 2018). "LATS1 immunoexpression was observed only in the cytoplasm of tumor cells in 59.3% of patients." (PMID 29850494, 2018). "The expression of LATS1 was significantly downregulated in the tumor tissues compared with the adjacent tissues (P < 0.001), and the Kaplan–Meier analysis indicated that the lower LATS1 expression was related to poor overall survival in patients with HCC (P = 0.032)." (PMID 28420424, 2017). "Moreover, the serine/threonine kinase LATS1 is a core kinase of Hippo kinase signaling pathway and plays important roles in tumor proliferation, apoptosis, and stem cell differentiation." (PMID 28420424, 2017). "However, Mst1/2 and Lats1/2 kinases are tumor suppressive, and their activity is low in many cancer types, unlike most oncogenic kinases, such as Src, Abl, Raf, and Akt, which are activated by mutations and involved in tumorigenesis." (PMID 28035075, 2017). "In fact, a similar tumor suppressor role for LATS1/2 has now been established in mammalian cells." (PMID 26621835, 2016). "Flow cytometry indicated that induction of apoptosis and cell cycle arrest by LATS1 may contribute to the tumor suppressive function." (PMID 26921249, 2016). "17-AAG, a potent Hsp90 inhibitor, disrupts LATS1 tumor suppressor activity in human cancer cells." (PMID 27759563, 2016). "Thus, MST1/2 and LATS1/2 would be tumour suppressors that negatively regulate by direct phosphorylation YAP1, which would behave as an oncogene." (PMID 27322327, 2016). "Disruption of LATS1 by heat shock protein 90 inhibitors promotes tumor proliferation, metastasis, and angiogenesis, indicating that LATS1 may act a pivotal role in the formation and progression of malignant tumors." (PMID 26921249, 2016). "Recent studies establish that Hippo/LATS/yes-associated protein (YAP) pathway is one major conserved mechanism governing cell contact inhibition, organ size control and cancer development 13, and LATS1/2 can function as the tumour suppressor genes in some cancers 14–16." (PMID 25712415, 2015). "Similarly, both Lats1 (−2.2-fold; p < 10−31) and Lats2 (−2.4-fold; p < 10−29), tumor suppressors that negatively regulate cell-cycle progression, showed a decrease in transcript levels." (PMID 25497456, 2015).